CRP (C-reactive protein)
Diseases named in the same sentence as CRP in open-access papers (continued):
Sharing a sentence is not in itself a finding about the gene and the disease.
breast cancer (continued). "MDD is associated with higher circulating levels of inflammatory cytokines, such as interleukin (IL)‐6, IL‐8, IL‐1β, TNF‐α, soluble IL‐2 receptor (sIL‐2R), and C‐reactive protein (CRP), which promote cellular proliferation in breast tissue and have also been linked to development of breast cancer." (PMID 35852181, 2023). "Chronic inflammation is an important cancer risk factor and meta-analyses haves associated CRP with breast cancer (HR = 1.14 [95% CI, 1.01–1.28]; OR = 1.23 [95% CI, 1.05–1.43]); colorectal cancer (OR = 1.34 [95% CI, 1.11–1.59]); and lung cancer (HR = 2.03 [95% CI, 1.59–2.50])." (PMID 36145186, 2022). "Postmenopausal women with an increased risk of breast cancer show improved hormonal (bioavailable estradiol, testosterone, and insulin) and adipocytokine (relative adiponectin/leptin, C-reactive protein) markers of breast cancer in serum and breast tissue with weight loss of more than 10%." (PMID 35752704, 2022). "Indeed, two recent studies found that elevated concentrations of circulating inflammatory markers such as C-reactive protein are associated with higher amygdala reactivity to social threat among women who have undergone treatment for early-stage breast cancer." (PMID 35431843, 2022). "However, in premenopausal women, leptin, the leptin-to-adiponectin ratio and CRP were inversely associated with breast cancer risk, while in postmenopausal women they were positively associated with breast cancer risk." (PMID 35430795, 2022). "In line, various analyses have demonstrated that elevated concentrations of the C-reactive protein are associated with colorectal cancer, pancreatic cancer, endometrial malignancies, and melanoma as well as postmenopausal breast cancer and are useful to indicate treatment resistance and/or survival." (PMID 35205678, 2022). "CRP, as an inflammatory marker, was reported to be associated with poor prognosis in breast cancer and increased significantly in the serum of patients with breast cancer metastasis." (PMID 35480092, 2022). "Univariate conditional logistic regression models showed that having a serum CRP or SAA level ≥ the median value was significantly associated with breast cancer relapse, with CRP OR 2.4 (95% confidence interval (CI) 1.16–5.00, p = 0.019) and SAA OR 3.38 (95% CI 1.57–7.25, p = 0.002)." (PMID 33483516, 2021). "In addition to ERK, SPHK1/S1P/S1PR3 axis has been implicated in potentiating the progression of breast cancer through upregulations of C-reactive protein (CRP) and MMP9." (PMID 34820423, 2021). "Additionally, circulating CRP concentration was positively associated with the risk of breast cancer (OR 1.43, 95% CI 1.02, 2.01)." (PMID 33557151, 2021). "This approach may allow us to elucidate an empirical pathway through which a substantial proportion of the susceptibility of GWA SNPs in CRP and IL-6 influences breast cancer risk through interactions with specific lifestyles." (PMID 33441805, 2021). "Previous studies disclosed stronger correlations between CRP and breast cancer risk in the first few years of follow-up, which might suggest consequences rather than causes of underlying cancer." (PMID 33435254, 2021). "Our findings may provide novel evidence on the immune-related molecular pathways linking to breast cancer risk and suggest potential clinical use of CRP to predict the specific cancer subtypes." (PMID 33614510, 2020). "In addition, genetically elevated CRP in our study was strongly associated with increased risk for ER/PR-positive breast cancer, which is consistent with recent findings." (PMID 33614510, 2020). "Also, genetically determined CRP was associated with increased breast cancer risk in obese groups (BMI ≥ 30; WHR > 0.85), despite a lack of statistical power." (PMID 33614510, 2020). "Similarly, the women in our study who had used OC for ≥5 years in the past had a strongly CRP-increased risk for breast cancer." (PMID 33614510, 2020).
breast cancer (continued). "Lastly, our study results may not be generalized to other races or ethnicity, in which the relationship between genetic instruments, CRP, and breast cancer risk may be different." (PMID 33614510, 2020). "Recent findings from a phase I clinical trial of patients with breast cancer treated with atezolizumab (anti-PD-L1) indicate that elevated baseline plasma levels of interleukin 6 (IL-6) and C-reactive protein (CRP) are associated with reduced progression free and overall survival." (PMID 33123173, 2020). "We tested the hypothesis that genetically determined CRP that interacts with lifestyles and breast cancer molecular subtypes has a potentially causal association with invasive breast cancer risk." (PMID 33614510, 2020). "However, this review found that only CRP has been extensively studied in association with breast cancer risk." (PMID 32731638, 2020). "The “Unhealthy/Pro-inflammatory” profile was positively loaded by the serum concentration of CRP, which has been positively associated with postmenopausal breast cancer in a prospective nested case-control study within the EPIC-Varese cohort study and several meta-analyses." (PMID 33202561, 2020). "While troponin I and CRP have been associated with changes in LVEF in patients undergoing chemotherapy for breast cancer, it is less well-reported with regards to early RT toxicity and there is similarly less consistent evidence to support BNP and NT-pro-BNP as an early biomarkers." (PMID 32903617, 2020). "Strengths of this analysis include the use of a MR approach to appraise the relationship of adipokines and CRP with breast cancer risk which should be less prone to confounding than conventional observational analyses and cannot be influenced by reverse causation." (PMID 32134113, 2020). "Obese women with mammary cancer also show a marked deregulation of insulin signaling, which causes an imbalance in cell proliferation, differentiation, apoptosis, altered expression of adipocytokines and C-reactive protein (CRP)." (PMID 32903534, 2020). "Until now, we have found only one published MR study on the CRP phenotype and breast cancer risk." (PMID 33614510, 2020). "In addition to pain, elevated pro-inflammatory cytokines, including CRP, after cancer treatment have been associated with persistent fatigue and sleep disturbances in breast cancer patients." (PMID 31138314, 2019). "Besides, stage III, PVI present and elevated high-sensitivity CRP were also associated with poor prognosis in patients with breast cancer (P<0.05)." (PMID 31262969, 2019). "Therefore, we aimed to examine the associations between CRP levels and RT-related pain among breast cancer patients who underwent adjuvant RT using a prospective study design." (PMID 31138314, 2019). "Moreover, the score was positively associated with inflammatory cytokines, including CRP and IL-6, which were also positively associated with the risk for overall mortality in patients with breast cancer." (PMID 30111758, 2018). "This study showed that a higher eating frequency was inversely proportional to serum CRP levels, suggesting that eating more frequently may lower systemic inflammation and subsequently reduce breast cancer risk." (PMID 29215604, 2017). "Specifically, the breast cancer incidence rate in these women was two-fold greater among those in the highest two quartiles compared with those in the lowest quartile of CRP, even after controlling for estradiol, insulin, BMI and established breast cancer risk factors." (PMID 27338371, 2016). "Besides, Hs-CRP, as an inflammatory biomarker, was superior to common CRP in predicting risk of breast cancer." (PMID 26001129, 2015). "A higher combined OR per natural log unit change in CRP was found in participants from Asia, which showed that regional differences might exist between the elevated levels of CRP and an increased risk of breast cancer." (PMID 26001129, 2015).
breast cancer (continued). "This meta-analysis assessed the association between CRP levels and breast cancer risk." (PMID 26001129, 2015). "Therefore, a meta-analysis of cohort studies and case-control studies was conducted to further clarify the association between the elevated levels of CRP and breast cancer risk." (PMID 26001129, 2015). "Our summary estimate of CRP and breast cancer risk in cohort studies was similar to that of another meta-analysis, which included 5 prospective studies with only 1,240 cases and reported a unit increase in ln(CRP) was associated with 10% increase in breast cancer risk." (PMID 26001129, 2015). "However, data evaluating the association between CRP and breast cancer risk is rare and inconsistent." (PMID 26001129, 2015). "Specifically, each 10 percent increase in the proportion of daily calories consumed after 5 pm was associated with a significantly higher concentration of CRP—a biomarker that has been associated with increased risk of breast cancer, as well as a variety of chronic conditions." (PMID 26305095, 2015). "Furthermore, we wanted to elucidate potential associations between pre-operative serum CRP and genes expressed in corresponding breast cancer specimen." (PMID 25340395, 2014). "Compared to the CC genotype, the combined CT and TT genotypes of TNFA-rs1799724 were associated with a 2.3-fold increased breast cancer risk (OR=2.31, 95% CI, 1.35-3.95), whereas carriers of the CRP-rs1205 T allele (CT and TT) had a 46% reduced risk (OR=0.54, 95% CI, 0.33-0.87)." (PMID 23991131, 2013). "Assessment of the association between use of NSAIDs and survival time may be worthwhile as lower levels of CRP have been linked with longer breast cancer survival and NSAIDs have been suggested as an adjuvant treatment for breast cancer." (PMID 22873489, 2012). "Elevated biomarkers of inflammation like CRP are associated with reduced survival among breast cancer patients which suggest that CRP may be related to tumor burden or progression and that chronic inflammation promotes mammary tumor development." (PMID 22646670, 2012). "Elevated plasma levels of C-reactive protein (CRP) may be associated with poor prognosis after breast cancer." (PMID 21639875, 2011). "So far, the present study is by far the largest study that has examined whether an association exists between CRP levels at the time of diagnosis and breast cancer prognosis." (PMID 21639875, 2011). "Mechanistically, three components might explain the observed association between elevated CRP levels and poor breast cancer prognosis." (PMID 21639875, 2011). "Thus, the combined evidence from this and our own study suggests that elevated plasma CRP levels are associated with short-term as well as long-term prognosis after breast cancer." (PMID 21639875, 2011). "Elevated levels of CRP are associated with reduced survival in breast cancer patients." (PMID 22276018, 2009). "We acquired data regarding C-reactive protein (CRP), interleukin (IL)-1a, IL-1b, and IL-6 expression and BC related to single nucleotide polymorphisms (SNPs) from two larger consortia (the genome-wide association studies and the Breast Cancer Association Consortium)." (PMID 38263420, 2024). "Similarly, research on breast cancer has illustrated that high serum hc-CRP levels could increase the risk of breast cancer." (PMID 37293590, 2023). "We performed a nested case-control study to examine whether pre-diagnostic circulating concentrations of adiponectin, leptin, c-reactive protein (CRP), tumour necrosis factor-α, interferon-γ and 6 interleukins were associated with breast cancer risk, overall and by menopausal status." (PMID 35430795, 2022). "Interestingly, our results further demonstrated a non-linear “increase-to-decrease” association pattern between CRP concentration and the breast cancer, which showed statistically significant heterogeneities for the associations between low (≤ 3mg/L) and high (> 3mg/L) CRP groups." (PMID 36117174, 2022).
breast cancer (continued). "Also, the evaluated NLR, PLR, and CRP levels were investigated to whether they could be considered potential breast cancer risk factors." (PMID 36532648, 2022). "However, other studies of SNPs in EB7H3 have identified associations with C-reactive protein (CRP) levels and plasma leptin levels in women, soluble leptin receptor levels, E. histolytica infection in children, luminal A breast cancer, tolerance for exercise intensity, and exercise participation." (PMID 34421692, 2021). "Moreover, elevated CRP at diagnosis was associated with poor prognosis in breast cancer." (PMID 33344503, 2020). "Thus, the results of the present study support the hypothesis that high CRP levels (>3000 ng/mL) are a risk factor for breast cancer among Chinese women." (PMID 30962499, 2019). "Moreover, a recent study of 84,000 individuals that looked for elevation of three inflammatory biomarkers (CRP, fibrinogen and leukocyte count) observed an increased risk of colorectal, lung and breast cancer, with greatest risk associated with elevation of all three." (PMID 27867087, 2017). "Indeed, some authors believed that excessive sleep might lead to elevated levels of systemic inflammation and increase some inflammatory biomarkers, such as CRP and IL-6, which might predispose an individual to breast cancer." (PMID 29130041, 2017). "So researchers proposed that serum CRP could be a marker of increased risk for breast cancer." (PMID 26693355, 2015). "For example, the systemic inflammatory response with elevated C-reactive protein (CRP) or serum amyloid A was reported to be associated with reduced survival, as demonstrated for several tumors like metastatic prostate, gastrooesophageal, colorectal, pancreatic or breast cancer." (PMID 26715527, 2015). "We used a prospective cohort study of 2,910 patients with invasive breast cancer to examine whether plasma CRP levels at the time of diagnosis of breast cancer are associated with overall survival, disease-free survival, death from breast cancer, and recurrence of breast cancer." (PMID 21639875, 2011). "We examined whether plasma C-reactive protein (CRP) levels at the time of diagnosis of breast cancer are associated with overall survival, disease-free survival, death from breast cancer, and recurrence of breast cancer." (PMID 21639875, 2011). "As CRP is one of several acute-phase proteins, whose concentrations increase during acute or chronic inflammation, other inflammation-related biomarkers may also be associated with breast cancer prognosis." (PMID 21639875, 2011). "Using a prospective cohort study of 2,910 Danish women with invasive breast cancer, we have demonstrated that elevated CRP levels at the time of diagnosis of breast cancer were associated with reduced overall and disease-free survival and with increased risk of death from breast cancer." (PMID 21639875, 2011). "Thus, it is unclear whether CRP levels measured at the time of diagnosis are associated with breast cancer prognosis." (PMID 21639875, 2011). "Recently, the systemic inflammatory response, as evidenced by elevated circulating concentrations of C-reactive protein and hypoalbuminaemia, has been shown to be independently associated with poorer survival in patients with advanced disease including breast cancer." (PMID 18797461, 2008). "In this study, we examined the impact of the ESP on the metabolomic profile, as well as levels of VEGF, cortisol, and CRP, in addition to its analgesic effects in breast cancer surgery." (PMID 40731923, 2025). "A total of 3 RCTs included 132 breast cancer patients to compare the differences in CRP levels between the mind–body exercise group and the control group." (PMID 41221238, 2025). "In breast cancer, inflammatory blood markers such as C-reactive protein (CRP), neutrophil-to-lymphocyte ratio (NLR), monocyte-to-lymphocyte ratio (MLR), and platelet-to-lymphocyte ratio (PLR) have emerged as important prognostic indicators." (PMID 40901118, 2025).
breast cancer (continued). "In recurrenced breast cancer, CRP levels were significantly higher than levels in non‐recurrenced patients due to more aggressive disease with higher tumor burden and poorer prognosis." (PMID 40791284, 2025). "Elevated pre-treatment CRP levels have been observed to correlate with tumor aggressiveness, poor treatment response, and unfavorable outcomes in breast cancer patients." (PMID 40416620, 2025). "Prior research indicated that CRP was generally elevated in breast cancer patients, suggesting its crucial role in the pathophysiology of inflammation in patients with metastatic breast cancer, which is associated with higher mortality." (PMID 40906676, 2025). "The result of the study is evidence that saliva can be used as an informative diagnostic biomaterial in relation to CRP, CYFRA 21-1, CA15-3, CA27.29, MCA, and CA19-9 in patients with breast cancer." (PMID 40699615, 2025). "It has previously been associated with prevalent breast cancer, incident COPD, an age-by-sex interaction and the levels of 17 proteins including CRP, SERPING1, CHAD and CGA." (PMID 41361833, 2025). "High-sensitivity CRP (hs-CRP) assays have shown potential in detecting early-stage breast cancer, with studies reporting a correlation between elevated CRP levels and tumor presence." (PMID 40901118, 2025). "Inflammatory markers were slightly elevated in the breast cancer group (CRP: 2.58 vs 2.49, SII: 604 vs 598, PIV: 271 vs 263)." (PMID 40679991, 2025). "In the context of breast cancer survivors, exercise-mediated reductions in proinflammatory biomarkers such as IL-6, TNF-α, and CRP have been linked with lower mortality, reduced recurrence risk, and lower hospitalization rates." (PMID 41303335, 2025). "At the systemic level, CRP reflects the presence of a systemic inflammatory process in the body, which can play an important role in the progression of breast cancer." (PMID 40699615, 2025). "This is supported by two RCTs conducted in breast cancer survivors, which demonstrated that combined caloric restriction and exercise interventions yielded greater improvements in glucose, leptin, and CRP levels than caloric restriction alone." (PMID 40895542, 2025). "Literature has reported that higher-intensity AE is linked to lowered levels of CRP, IL-6, and TNF-α, and this has been determined in breast cancer." (PMID 41480347, 2025). "AE directly modulates the inflammatory milieu by reducing the levels of key pro-inflammatory cytokines such as TNF-α, IL-6, and CRP, as evidenced in breast cancer studies." (PMID 41480347, 2025). "Although LDH, CRP, and Alb levels have been reported as prognostic factors in advanced recurrent breast cancer, these previous studies included patients with a poor nutritional status." (PMID 38965074, 2025). "Higher age, metastases other than plasmacytoma/renal cell/breast carcinoma, pathologic fracture or >1 metastases and elevated CRP values were independent predictors of shorter postoperative patient survival." (PMID 40105218, 2025). "In this large prospective cohort study, higher levels of CRP, SII, CAR, CLR, MHR, and NHR were associated with an increased risk of breast cancer, albeit LMR was inversely associated with breast cancer." (PMID 38360584, 2024). "Another challenge in data collection was the relative paucity of CRP tests performed on breast cancer patients at diagnosis." (PMID 37673801, 2024). "Among these markers, CRP and CAR also mediated the largest extent of the associations between diet score and physical activity with breast cancer." (PMID 38360584, 2024). "In our study, novel inflammation markers related to CRP and HDL-c were associated with breast cancer risk, while traditionally systemic inflammation markers such as PLR and NLR were not." (PMID 38360584, 2024). "Physical exercise has been shown to lower circulating levels of interleukins (IL-6 and IL-8), tumour necrosis factor (TNF) α and C-reactive protein (CRP) in breast cancer survivors after treatment." (PMID 37686583, 2023).